TLR4 (toll like receptor 4)
Diseases named in the same sentence as TLR4 in open-access papers (continued):
Sharing a sentence is not in itself a finding about the gene and the disease.
tumor (continued). "Here, higher TLR4 mRNA level was found in BC tumor when compared with paracancerous tissue." (PMID 38833016, 2024). "Furthermore, in vitro experiments have confirmed that paclitaxel reprogrammes M2 polarized macrophages into M1-like phenotypes in a TLR4-dependent manner, promoting the effectiveness of anti-tumor immunotherapy." (PMID 39161779, 2024). "TLR4 gene is expressed in all three tumor models studied in the present work." (PMID 39553439, 2024). "Hypoxia-induced necrotic fragments of cancer cells, like HCC cells, and HIF-1α secreted by hypoxic tumor cells recruit TLR4 to the macrophage cell membrane, activating the toll-like receptor (TLR) 4/TIR-domain-containing adaptor-inducing interferon-β (TRIF)/NF-κB pathway." (PMID 39430253, 2024). "Tie2+ monocytes express a number of tumor-promoting genes including Mmp9, Vegfa, Cxcl12, Tlr4, Nrp1, and Pdgfb at a high level, and their pro-angiogenic potential could be further stimulated by EC-derived factors in the perivascular niche." (PMID 38580870, 2024). "Moreover, a study by Pan and colleagues investigated development of a potent anti-tumor vaccine co-loaded with stearic acid-doped lipid nanoparticles (sLNPs), OVA-encoding mRNA, and a TLR4 agonist, monophosphoryl lipid A (MPLA)." (PMID 39339880, 2024). "Research indicates that simvastatin and atorvastatin may prevent EAC tumor growth by inhibiting the TLR4 pathway." (PMID 38169510, 2024). "We found that curcumin suppressed tumor progression via the TLR4/HIF-1α/PD-L1 pathway, suggesting that curcumin may be a potent immunomodulator for treating CRC." (PMID 38612546, 2024). "As a tumor suppressor, ECRG4 is downregulated in cancers due to promoter methylation, and its immune activation and tumor inhibition functions may be attributed to its TLR4-targeted internalization domain." (PMID 38833013, 2024). "Despite the potential anti-tumor effects of TLR4 in DCs, several studies have suggested that TLR4 could also mediate tumor-promoting effects." (PMID 39238498, 2024). "When the tumor is irradiated, the release of HMGB1 from damaged tumor cells may lead to NETs formation in a TLR4‐dependent manner." (PMID 39015554, 2024). "However, TLR4 activation on IECs fosters a tumor-promoting microenvironment, contributing to CAC tumorigenesis." (PMID 38930793, 2024). "Additionally, the frequencies of tumor antigen-specific CD8+ T cells were decreased in the TME of TLR2-KO or TLR4-KO mice compared to that of WT mice." (PMID 38792006, 2024). "We assessed tumor inflammation by morphological evaluation of the inflammatory infiltration of surrounding tumors, and we found a statistically significant correlation between TLR4 downregulation and inflammatory infiltration in the tumor microenvironment." (PMID 39451550, 2024). "Clinical trials targeting metastatic soft tissue sarcomas have shown promising results with the intratumoral injection of the TLR4 agonist glycopyranosyl lipid A in a stable-emulsion formulation, combined with concurrent radiotherapy, achieving effective local control of the tumor." (PMID 38523155, 2024). "MMP12 might promote Foxp3+Treg infiltration in tumor tissue; TLR4 might obliquely attract Foxp3+Treg to the tumor location by interacting with TGF-β and macrophages." (PMID 38919615, 2024). "Notably, the mutation frequencies of key ICDRGs, such as PI3KA, NLRP3, CASP8, and TLR4, highlight the potential role of genetic alterations in modulating immune responses within the tumor microenvironment." (PMID 39372411, 2024). "In addition, FOXP3 expression was also associated with TNM-stage and lymph node metastasis, which was correlated with the interaction of FOXP3 and TLR4 in tumor cell escape and subsequent tumor progression." (PMID 38674427, 2024). "In general, constitutive TLR4 signaling tends to support pro-tumorigenic functions, whereas regulated or therapeutic TLR4 activation may promote anti-tumor immunity." (PMID 38903515, 2024).
tumor (continued). "Reducing tumor cell TLR4 expression decreases metastatic tumor burden in steatotic livers in CRC." (PMID 38930793, 2024). "Activation of TLR4 on immune cells has shown efficacy in inhibiting tumor growth." (PMID 38930793, 2024). "Furthermore, pharmacologic inhibition of TLR4 with a cell permeable inhibitor or depletion of HMGB1 using neutralizing antibodies or HMGB1-specific siRNA reduced the efficacy of anti-tumour vaccination." (PMID 38353760, 2024). "A recent clinical trial revealed that the standard GBM therapy incorporated with the administration of HSPPC-96, as a TLR4 agonist derived from a patient's tumour, potentiated infiltration of CD8+ and CD4+ T cells in the injected tumours and upregulated the immune-related genes." (PMID 38698968, 2024). "In glioma, TLR4 signaling appears to have a dual role in tumor development and progression." (PMID 39594997, 2024). "Further, WB results exhibited that curcumin was able to inhibit HIF-1α and PD-L1 expression in the inflammatory environment established by LPS-stimulated CT26 cells, suggesting that curcumin suppressed tumor immune escape by inhibiting the TLR4/HIF-1α/PD-L1 pathway." (PMID 38612546, 2024). "Additionally, the dysregulation of microbiota can promote the proliferation, invasion and metastasis of tumor cells by increasing the release of endotoxin and mediating the M2 polarization of TLR4-dependent macrophages." (PMID 38835371, 2024). "HSPs, therefore, may serve as functional associated activators with the CDK7/CDK9–Rpb1 complex, akin to TLR4 activation in tumor-induced muscle wasting." (PMID 38858714, 2024). "Interestingly, there was a significant correlation between TGF-β, IL-6, TLR-2 and TLR-4 in the primary CRC tumor and SPP1 expression by macrophages in the metastatic intrahepatic tumor." (PMID 39372792, 2024). "Furthermore, in the presence of CLI-095, a TLR4 inhibitor, the rapid endocytic uptake of Ahsg is inhibited, resulting in a decline in the adhesion of tumor cells as well as invasion through a bed of Matrigel." (PMID 39684629, 2024). "Their study showed that bacterial stimulation of tumor cells through TLR4 might promote tumor survival and induce chemoresistance, which could be protumorigenic." (PMID 39238498, 2024). "The autophagosome TRAP released by tumor cells induces macrophages to polarize to the M2 phenotype and upregulates PD-L1 and IL-10 expression in TAMs through the TLR4-MyD88-p38-STAT3 signaling pathway, suppressing T cell proliferation and promoting tumor growth." (PMID 38762484, 2024). "Altogether, the activation of the TLR4 pathway by PTX in combination with TGFβ inhibition can further invigorate the immune tumor microenvironment across tumor models, which may explain the robust performance of the combination treatments." (PMID 39553439, 2024). "Finally, intratumoral administration of AdjFluVx was found to significantly upregulate TLR4 expression on tumor localized myeloid derived suppressor cells (MDSCs)." (PMID 38476365, 2024). "Indeed, TGF-β induced miR-182 has been shown to modulate the TLR4/NF-κB signalling pathways, indicating its role in tumour progression." (PMID 39041944, 2024). "This suggests that the commensal microbiota in breast tissues may contribute to tumor growth through a novel LPS/S100A7/TLR4/RAGE axis." (PMID 39830522, 2024). "The mRNA level of TLR4 in tumor tissue treated with LPS was significantly improved compared with that treated with saline, which could be used as a positive indicate of LPS efficiency used for treatment." (PMID 37553698, 2023). "Overexpression of TLR4 has been identified in HCC tumor samples." (PMID 36845131, 2023).
tumor (continued). "The paradox was encountered when further in-depth analyses revealed that contrary to our hypothesis, ART significantly downregulated CLEC12A expression, and increased the expression of TLR4 in the presence of ART in tumor tissues." (PMID 38144525, 2023). "NETs could activate TLR4-mediated p38-PGC1α signaling pathway, which causes increased mitochondrial biogenesis in metastatic CRC cells and eventually contributes to tumor growth." (PMID 36050539, 2023). "In a similar study, TLR4 expression was positively correlated with tumor differentiation." (PMID 37112730, 2023). "Likewise, activation of TLR-4 and processing of tumor antigens stimulate DC maturation to markedly increasing in vivo CD8+IFNγ+ cytotoxic T cells." (PMID 37936697, 2023). "Another factor which was attributed was TLR4- mediated signaling which could be important for tumor colonization and anti- tumor efficacy." (PMID 38090593, 2023). "Once dimerization occurs, TLR-4 activates various downstream signaling pathways, inducing inflammatory responses, and activating monocytes (macrophages and DCs) and neutrophils, thereby enhancing the immune response and promoting tumor killing." (PMID 37103820, 2023). "Besides, both L. casei & L. reuteri and TAK-242 profoundly inhibited TLR4, MyD88, and Ki67 expressions in tumor tissues." (PMID 37904102, 2023). "Nevertheless, TLR4 activation generally plays an ambivalent role during tumor progression." (PMID 36614179, 2023). "Mechanistically, NE as NETs-derived stimulatory factor directly activated the TLR4 pathway on tumor cells and subsequently upregulated Peroxisomes proliferator-activated receptor gamma coactivator 1-alpha (PGC1-α), driving mitochondrial homeostasis and favoring the tumor growth." (PMID 36859358, 2023). "Previous studies have demonstrated that RPLP2 functions as a pattern-associated molecular pattern (PAMP) that extracellularly binds to TLR4 on dendritic cell surfaces, thereby inducing dendritic cell maturation and activation in a TLR4-dependent manner and ultimately exerting tumour-immune effects." (PMID 38052785, 2023). "In addition, curcumin also induces tumor cell apoptosis by suppressing the heat shock protein 60 (HSP60)/Toll-like receptor 4 (TLR-4)/myeloid differentiation primary response 88 (MYD88)/NF-κB pathway." (PMID 37373484, 2023). "In the in vivo experiment, knockdown of TLR4 significantly inhibited tumor growth in nude mice." (PMID 38062041, 2023). "We hypothesized that tumor cells may metabolically reprogram TME cells in HCC through the HSPA1-GRIN2D/TLR4 axis to promote tumor progression." (PMID 37914817, 2023). "The key role of the SNHG1/miR-140/TLR4/NF-κB signaling axis in CCA tumorigenesis and progression has been established, indicating that TLR4 expression promotes cell proliferation and angiogenesis and inhibits apoptosis, stimulating tumor invasion and metastasis." (PMID 37345131, 2023). "TLR-4 inhibition of host anti-tumor activity is also controversial, because, if it is true that tumor progression involves TLR-4-mediated production of pro-inflammatory and immunosuppressive cytokines, TLR-4 antagonists reduce pro-inflammatory response, but also compromise host immunity." (PMID 36838231, 2023). "It has been found that the infection-mimicking polyglutamic acid, at 5 kDa, can be successfully used as an immunoadjuvant to effectively elicit an anti-tumour immune response in a dose-dependent manner, with stimulation of toll-like receptor 4 having been suggested as a mechanism." (PMID 36319895, 2023). "Additionally, TLR4 activation seems to be mediated by peroxiredoxin 1 (an antioxidant enzyme elevated and secreted by tumor prostate cells) conferring chemoresistance in PC-3 cells." (PMID 37819510, 2023). "We hypothesized that this monocyte subset (JAK3+TLR4+ CD16 monocyte) contributes to shaping pro-tumor immunity in TME, ultimately accelerating malignant transformation and tumor progression." (PMID 38149248, 2023).
tumor (continued). "LPS as a known stimulator for TLR4 suppressed tumor growth in vivo." (PMID 37553698, 2023). "For its part, NE may trigger TLR-4 signaling pathways in colorectal cancer cells, resulting in the upregulation of proteins involved in tumor mitochondrial biogenesis and growth." (PMID 36983067, 2023). "TLR4 expression relative to tumor stage is well documented in the literature." (PMID 35841426, 2023). "Until recently, it was thought that TLR-4-induced inflammation might have two distinct effects on tumor therapy." (PMID 37103820, 2023). "The mechanisms underlying the action of Fusobacterium could range from increasing tumor cell adherence and invasion to influencing the host immune response and activating the Toll-like receptor 4 pathway." (PMID 37313408, 2023). "Mice transferred with splenocytes from previous OAd-MSC WT and of OAd-MSC TLR4−/− groups showed a trend toward decreased tumor growth compared to those treated with splenocytes from PBS group, which confirmed the presence of antitumor immunity triggered by the cell-based virotherapy." (PMID 36875156, 2023). "Additionally, in CD16 monocytes, the remaining NPA genes, JAK3, PPIA, and TLR4 were up-regulated in tumor tissues, while IFNGR1 was down-regulated in tumor samples." (PMID 38149248, 2023). "After a battery of studies, it was shown that a NE drug carrier system including spirulina polysaccharides and PTX has the ability to boost PTX's anti-tumor impact by modulating immunity through Toll-like receptor 4/nuclear factor kappa B (TLR4/NF-B) signaling pathways." (PMID 37814270, 2023). "In addition, the OM group had significantly reduced expression of Toll-like receptors (TLR4) and IL-18 relative to the OL group, contributing to the tumor’s immune escape." (PMID 38260202, 2023). "Overexpression of TLR4 in malignant cells promotes tumor growth and metastases." (PMID 37370894, 2023). "Eiro and colleagues reported TLR4 expression by fibroblasts, not tumor cells themselves, was associated with a shortened OS of CRC participants (P = 0.022)." (PMID 35841426, 2023). "Previous study suggested that TLR4 could facilitate tumor cells invasion and migration as a cancer stem cell marker in HCC." (PMID 37251918, 2023). "Separate administering specific inhibitors of mammalian target of rapamycin (mTOR) and NF-κB pathways, such as rapamycin and BAY11–7082, to block each key nodal pathway showed that tumor-secreted CTSK combined with TLR4 via the mTOR-dependent pathway stimulates TAMs to polarize toward M2 phenotype." (PMID 37943609, 2023). "In the tumor microenvironment, not only MDSCs, but also tumor cells can express TLR4." (PMID 36932197, 2023). "Secretin tumour cell line 1 enteroendocrine cells were treated for 24 or 48 h with toll-like receptor agonists (toll-like receptor 4 selective lipopolysaccharide; toll-like receptor 2 selective Pam3CysSerLys4) and the free fatty acid receptor 2/3 agonists butyrate, propionate and acetate." (PMID 37953845, 2023). "We speculated that the higher migration of OAd-MSC TLR4−/− to the tumor site could generate high local inflammation in the tumor microenvironment." (PMID 36875156, 2023). "This is in keeping with the impact observed on the immune system, namely the activation of monocytes and neutrophils in vitro, as well as the recruitment at tumor site of several innate cells, notably TLR4+ macrophages and neutrophils observed in mice exposed to F1Lipo-LPS." (PMID 37223101, 2023). "Studies have suggested that TLR4 signaling might be involved in several aspects of hepatocarcinogenesis, including tumor growth, invasion, and metastasis." (PMID 37896221, 2023). "Importantly, we demonstrate that the pro-tumor activity of PTX3 is exerted via the activation of the TLR4 pathway which is known to play a relevant role in TNBC aggressiveness." (PMID 37749607, 2023).
tumor (continued). "By inducing TLR-4 dimerization with small-molecule agonists, downstream signaling pathways can be activated to generate a strong pro-inflammatory response to kill tumor cells, which may have important implications in anti-tumor immunity." (PMID 37103820, 2023). "The alarmin protein HMGB1, which could be secreted by dying tumor cells in circulation, is a natural ligand of toll-like receptor 4 (TLR4) present on platelet surfaces." (PMID 37770941, 2023). "Altogether, our findings suggest that the direct targeting of PTX3 or TLR4 may represent a promising novel therapeutic approach for the treatment of TNBC as well as other tumor types where TLR4 signaling activation strictly depends on PTX3 expression." (PMID 37749607, 2023). "Pre-clinical CRC models indicate that TLR4 has both pro- and anti- tumor roles, with expression sites being a possible differentiating factor between whether TLR4 aids in cancer destruction or survival." (PMID 35841426, 2023). "The TLR4-MyD88-dependent signaling pathway can activate transcription factors such as NFκB and activatorprotein-1 (AP-1), before activating related immune cells to play the role of immunosuppression and promote the development of tumor disease." (PMID 38074679, 2023). "Moreover, NETs have been shown to be able to capture tumor-platelet aggregates in a hepatic I/R injury model, possibly through interactions between NETs and TLR4-activated platelets." (PMID 36050539, 2023). "In this frame, our data indicate that PTX3 secreted by tumor cells promotes the activation of the TLR4/IRAK1 pathway in TNBC cells, and that the expression of PTX3 itself may determine the antitumor responses to TLR4 inhibition." (PMID 37749607, 2023). "TLR4 induces an effective cytotoxic T cell immune response to tumour antigens." (PMID 36936437, 2023). "M1 macrophages stimulated with low-dose Lipo-MP-LPS may however present reduced anti-tumor effects as some studies showed that low doses of TLR4 agonists may turn macrophages toward a tolerant state and M2 phenotype." (PMID 37760603, 2023). "Furthermore, Huang (2018) found that improvement in clinical outcome is resultant of cytosolic HMGB1 triggering dendritic cell maturation through TLR4 activation, whereby consequently recruiting PD-1+ tumor-infiltrating lymphocytes to the tumor site." (PMID 35841426, 2023). "The findings suggest that TLR4-controlled immunity supports senescence induction and the expression of DNA repair proteins, which play an integrated defense role against genotoxic carcinogenesis and tumor progression in the liver." (PMID 37896221, 2023). "In particular, the expression of TLR4 was detected at a higher level in U118, U87, A172, and LN229 glioma cell lines, and such high expression was linked with the regulation of cell growth and survival of the tumor cells." (PMID 37822929, 2023). "RT-qPCR was utilized to assess TLR4 and MyD88 expressions in pancreatic cells or tumor tissues." (PMID 37904102, 2023). "A possible reason might be the impaired TLR4/LPS pathway in alveolar macrophages from tumor tissues, but the details are still fuzzy." (PMID 36932407, 2023). "A recent study demonstrated that surgical stress-activated platelets facilitated NETs-mediated capture of CTCs and synergized with the enhanced aggregation of platelet–tumor cells, contributing to distant metastasis via the Toll-like receptor 4 (TLR4)-ERK5-integrin GPIIb/IIIa axis." (PMID 36937386, 2023). "The effect however could not be reproduced in TLR4 null macrophages, corroborating that tumor-derived redHMGB1, via TLR4-sensing pathway, initiated the mTOR/Bcl6 program in macrophages." (PMID 36542153, 2022). "Any treatment that modifies TLR4 signalling may have protective effects for the intestine while also increasing anti-tumour activity during chemotherapy." (PMID 35962138, 2022). "Although necrosis is a form of cell death, it may lead to the progression of tumor growth through the TLR-4-dependent mechanism." (PMID 36142391, 2022).